GADD45A (growth arrest and DNA damage inducible alpha)
Description:
In T-cells, functions as a regulator of p38 MAPKs by inhibiting p88 phosphorylation and activity (By similarity). Might affect PCNA interaction with some CDK (cell division protein kinase) complexes; stimulates DNA excision repair in vitro and inhibits entry of cells into S phase.
Synonyms: DDIT1; GADD45
Tractability: Small molecule: it has a high-quality binding pocket. PROTAC: ubiquitination databases record sites on it.
Gene: Protein-coding gene on chromosome 1 (67,685,201 to 67,688,334, forward strand). Ensembl gene ENSG00000116717.
Subcellular location: Nucleus
Subcellular location (Human Protein Atlas): Nuclear speckles
Pathways (Reactome):
Gene expression (Transcription): FOXO-mediated transcription of cell cycle genes
Gene Ontology:
Molecular function: kinase binding; protein binding; protein heterodimerization activity; protein homodimerization activity; promoter-specific chromatin binding
Biological process: cellular response to ionizing radiation; cellular response to mechanical stimulus; negative regulation of blood vessel endothelial cell migration; negative regulation of peptidyl-serine phosphorylation of STAT protein; negative regulation of protein serine/threonine kinase activity; negative regulation of transcription by RNA polymerase II; positive regulation of apoptotic process; positive regulation of JNK cascade; positive regulation of p38MAPK cascade; positive regulation of reactive oxygen species metabolic process; signal transduction in response to DNA damage; apoptotic process; DNA repair; regulation of cell cycle; regulation of cyclin-dependent protein serine/threonine kinase activity; negative regulation of angiogenesis
Cellular component: cytoplasm; nuclear speck; nucleus; nucleoplasm
Genetic constraint (gnomAD): Loss-of-function variants: 5 observed, 13.46 expected, observed/expected ratio (o/e) 0.37, 90% interval 0.19 to 0.78. The upper end of that interval is the gene's LOEUF score, 0.78, which puts it in group 3 of 6, group 1 being the genes least tolerant of losing a copy. Missense variants: 123 observed, 182.97 expected, observed/expected ratio (o/e) 0.67, 90% interval 0.58 to 0.78. Synonymous variants: 82 observed, 84.99 expected, observed/expected ratio (o/e) 0.96, 90% interval 0.81 to 1.16.
Homologues: Orthologues: chimpanzee GADD45A (100% identical), macaque GADD45A (99% identical), rabbit GADD45A (98% identical), dog GADD45A (96% identical), mouse Gadd45a (95% identical), rat Gadd45a (93% identical), guinea pig GADD45A (91% identical), pig GADD45A (72% identical), zebrafish gadd45ab (70% identical), tropical clawed frog gadd45a (67% identical), zebrafish gadd45aa (65% identical), Drosophila melanogaster Gadd45 (29% identical). Paralogues in human: GADD45G (55% identical), GADD45B (55% identical).
Diseases named in the same sentence as GADD45A in open-access papers:
GADD45A is named in the same sentence as 197 diseases in open-access papers, as found by Europe PMC text mining. Sharing a sentence is not in itself a finding about the gene and the disease. The quoted sentences say what the papers report.
breast cancer (52 papers, 2006 to 2025). A primary or metastatic malignant neoplasm involving the breast. "Immunohistochemical detection of GADD45A in normal and breast tissue samples revealed that its level was strongly associated with hormone receptor status in human breast cancer." (PMID 32456160, 2020). "In conclusion, Gadd45a levels in human breast cancer are significantly associated with hormone receptor status." (PMID 23706118, 2013). "More recently, evidence was obtained that loss of Gadd45a accelerates ras-driven mammary tumor formation." (PMID 18789159, 2008). "GADD45A overexpression is associated with a favorable prognosis, which suggests that the abnormal methylation of GADD45 may contribute to breast cancer risk." (PMID 26422378, 2015). "Also, BRCA-1-mediated induction of gadd45a has been implicated in apoptosis of breast cancer cells, whereas gadd45g expression was shown to have a role in neuronal cell death." (PMID 18789159, 2008). "Promoter hypermethylation underlies GADD45A downregulation in breast cancer." (PMID 17280610, 2007). "Promoter methylation of GADD45A has been observed in several types of human cancers, including breast cancer and lung cancer." (PMID 39728572, 2024). "It was reported that GADD45A was overexpressed in pancreatic ductal adenocarcinoma and breast cancer at both mRNA level and protein level." (PMID 39458909, 2024). "By elucidating its mechanism of action, particularly through the regulation of GADD45A and associated pathways, we offer valuable insights into the therapeutic potential of NF113 as a targeted therapy for breast cancer." (PMID 39458909, 2024). "Previously, TRIB3 was shown to be induced by hypoxia (0.1–0.5% O2) in breast cancer cells and in rat pulmonary artery smooth muscle cells (5% O2), Expression of Ddit4 and Gadd45a were previously shown to be increased under hypoxia and oxidative stress." (PMID 37656229, 2023). "Based on the data from the TCGA database using UALCAN analysis, GADD45A was lowly expressed in various types of cancer, including breast cancer." (PMID 35308218, 2022). "GADD45A expression was also strongly correlated with trametinib response in breast cancer (ρ = -0.7012; pFDR = 0.0399)." (PMID 33676569, 2021). "They observed that normal breast tissue was characterized by low levels of GADD45A, but high levels of this protein were observed in luminal A and B types of breast cancer." (PMID 32013256, 2020). "Patients with higher GADD45A expression levels had a poorer long-term prognosis in TN type breast cancer." (PMID 30128181, 2018). "The aim of the current study is to investigate the significance of GADD45A in breast cancer, including the correlation with clinicopathologic factors and long-term survival situation." (PMID 30128181, 2018). "GADD45A expression levels are significantly correlative with estrogen receptor status and Ki-67 index in human breast cancer." (PMID 30128181, 2018). "In research on esophageal squamous cell carcinoma (ESCC) and another article on breast cancer, GADD45A protein levels were increased significantly in tumor tissues than those in normal tissues." (PMID 30128181, 2018). "Correlation between high/low GADD45A expression and clinic pathological factors in 419 breast cancer tissues." (PMID 30128181, 2018). "Compared with the previous study for GADD45A in breast cancer, our study had a larger sample analysis for the correlations between clinicopathological factors and GADD45A expression." (PMID 30128181, 2018). "Despite the limitations, the correlation between GADD45A expression and certain clinicopathological factors in breast cancer can be verified." (PMID 30128181, 2018). "In present study, we explored the expression and clinical significance of GADD45A in breast carcinoma." (PMID 30128181, 2018). "GADD45a is reported to promote Myc-driven breast cancer, resulting in increased tumor vascularization and growth." (PMID 29212169, 2017).
breast cancer (continued). "Among this short list, GADD45A, TANK and TACC2 are already known risk related factor in breast cancer." (PMID 28621677, 2017). "In contrast, Gadd45a functions to promote Myc-driven breast cancer by negatively regulating MMP10 via GSK3B/B-catenin signaling, resulting in increased tumor vascularization and growth." (PMID 23706118, 2013). "Statistical analyses were performed to examine the correlation between Gadd45a expression levels and various clinicopatholgical characteristics of breast cancer." (PMID 23706118, 2013). "Taken together, these data provide evidence that Gadd45a expression in breast cancer is elevated in Luminal A and Luminal B human breast cancer." (PMID 23706118, 2013). "Our data presented here provides evidence that elevated expression of Gadd45a correlates with ER+/PR+, Luminal A and Luminal B breast cancers, whereas low expression of Gadd45a correlates with ER-/PR-, Her2+ and Triple Negative breast cancers." (PMID 23706118, 2013). "Further studies are indicated to elucidate the role of Gadd45a in breast cancer as a potential prognosticator or target for treatment." (PMID 23706118, 2013). "The present study was aimed at clarifying the expression of Gadd45a in human breast cancer and correlation of its expression with clinicopathologic features, such as hormone receptor status." (PMID 23706118, 2013). "We found that Gadd45a was significantly overexpressed in breast cancer tissues compared to normal tissues obtained from patients who underwent reduction mammaplasty." (PMID 23706118, 2013). "This difference in distribution of Gadd45a levels across breast cancer receptor subtypes was significant, P = 0.0009." (PMID 23706118, 2013). "The observed differences in Gadd45a expression within the various breast cancer subtypes was statistically significant (P < 0.001, ANOVA)." (PMID 23706118, 2013). "We demonstrate for the first time that the expression levels of Gadd45a are hormone receptor status dependent, where high levels of Gadd45a correlate with ER+/PR + breast cancers." (PMID 23706118, 2013). "The present study was aimed at clarifying the expression of Gadd45a in human breast cancer and its correlation with clinicopathologic features." (PMID 23706118, 2013). "Taken together, these observations demonstrate that high levels of Gadd45a expression are correlated with the development of primary breast carcinoma." (PMID 23706118, 2013). "Gadd45a protein levels are elevated in human breast carcinoma, demonstrated by immunohistochemical staining." (PMID 23706118, 2013). "Gadd45a inhibits mammary tumor growth through p38-mediated cellular senescence." (PMID 36945044, 2023). "When BRCA1 induces GADD45A in breast cancer, it may lead to apoptosis through the JNK pathway and interaction with MTK1/MEKK4." (PMID 32013256, 2020). "The important role of GADD45A in cancer transformation was also confirmed in breast cancer." (PMID 32013256, 2020). "Some associations between variability of the GADD45A gene and the occurrence of breast cancer with no BRCA1/2 mutation (sporadic and familial) were found in a large cohort study performed in a Chinese population." (PMID 32013256, 2020). "BRCA1 also interacts with GADD45A (growth arrest and DNA damage-inducible protein GADD45 alpha) that may target NER machinery to actively demethylate genome sites in order to change the expression of genes that may be important in breast cancer." (PMID 32013256, 2020). "In the present study, we found that AME can cause S-phase arrest of breast cancer cells, downregulate the expression of CDC20, AURKB, PLK1, CCNB2, and TOP2A, and upregulate the expression of GADD45A, eventually inhibiting the proliferation of breast cancer cells." (PMID 31275405, 2019). "Here, we studied the expression and clinical significance of GADD45A in breast cancer." (PMID 30128181, 2018). "In our opinions, this mechanism may result for the high GADD45A expression in breast cancer tissues." (PMID 30128181, 2018).
breast cancer (continued). "We found that GADD45A expression was upregulated in breast cancer tissues." (PMID 30128181, 2018). "From this, we considered that GADD45A may be a biomarker for the malignancy grade of breast cancer tissue." (PMID 30128181, 2018). "Our study suggested that GADD45A may play a role in breast cancer pathogenesis and may eventually help in understanding the biological mechanisms affecting tumor progression." (PMID 30128181, 2018). "Also, some research showed GADD45A can promote or suppress breast carcinoma development depending on different signaling pathways." (PMID 30128181, 2018). "In this study, we report for the first time the expression pattern of Gadd45a in breast cancer." (PMID 23706118, 2013). "Therefore, we choose to examine the expression patterns of these known Gadd45a effector proteins to provide insight into the functional role of Gadd45a in human breast cancer." (PMID 23706118, 2013). "Taken together, our work provides evidence that Gadd45a may play a role in breast cancer pathogenesis and may represent a novel prognostic factor for breast cancer." (PMID 23706118, 2013). "In combination with other biomarkers of breast cancer, Gadd45a expression status may be useful for determining which therapeutic strategies against breast cancer are employed." (PMID 23706118, 2013). "Our results suggest that Gadd45a may play a role in breast cancer pathogenesis and could be used as a biomarker for breast cancer prognosis." (PMID 23706118, 2013). "Thus, additional experiments must be carried out to elucidate the molecular mechanism of Gadd45a modulation of human breast cancer." (PMID 23706118, 2013). "Previously published studies have shown that Gadd45a plays a role in murine breast carcinoma." (PMID 23706118, 2013). "Similarly, GADD45A is highly involved in the regulation of stress-related regulation of cell survival and stressful growth arrest conditions, and expression levels were found to be upregulated in breast cancer." (PMID 37624039, 2023). "Interestingly, GADD45A is abnormally methylated in breast cancer." (PMID 36185256, 2022). "Therefore, the expression of GADD45A may be a prognostic marker in breast cancer and GADD45A may thus be considered a target in breast cancer therapy." (PMID 32013256, 2020). "Therefore, the protective action of GADD45A in Ras-driven breast cancer may include its cytotoxic and cytostatic action in breast cancer cells and so this protein can be considered a target in breast cancer therapy." (PMID 32456160, 2020). "In addition, BRCA1 may stimulate GADD45A-mediated nucleotide excision repair and DNA demethylation in breast cancer." (PMID 32456160, 2020). "Amongst them, GADD45A expression was upregulated in both the apoptosis and cell cycle arrays, which is consistent with previous studies showing that increased GADD45A expression leads to cell cycle arrest and apoptosis in a range of cell types, including breast cancer cells." (PMID 31601253, 2019). "Moreover, investigation of mechanisms that regulate Gadd45a expression during breast carcinogenesis and a more complete understanding of the role Gadd45a expression and signaling play in breast cancer pathogenesis may provide novel therapeutic targets." (PMID 23706118, 2013). "Gossypol upregulates apoptosis-promoting genes such as those involved in growth arrest and DNA damage-inducible 45 alpha (GADD45A), tumor necrosis factor receptor superfamily 9, and BCL2-interacting protein 3 in breast cancer cells." (PMID 35283426, 2022). "Increased expression of GADD45A, PUMA, p21 and PAI-1 correlates with better prognosis in patients with ERα-positive breast cancer after endocrine therapy and chemotherapy." (PMID 29854295, 2018). "In addition, METTL1 inhibited breast cancer (BC) cell cycle progression and proliferation by promoting the translation of growth arrest and DNA damage 45 alpha (GADD45A) and retinoblastoma protein 1 (RB1) mRNAs, selectively blocking the G2/M phase of the cell cycle." (PMID 39979979, 2025).
breast cancer (continued). "The analysis revealed a significant upregulation of ESR1 expression in breast cancer tissues compared to their non-tumoral counterparts, whereas GADD45A exhibited a contrasting downregulation in tumoral tissues." (PMID 38732206, 2024). "A higher expression of GADD45A was observed in breast cancer samples compared with adjacent non-cancerous tissues." (PMID 32013256, 2020). "We performed an immunohistochemical study of GADD45A protein from 419 breast cancer tissues and 116 adjacent non-neoplastic tissues." (PMID 30128181, 2018). "Significantly high GADD45A expression were observed in breast cancer tissues compared with adjacent non-neoplastic tissues (P < 0.001) and were independently correlative with estrogen receptor negative (P = 0.028) and high Ki-67 index (P < 0.001)." (PMID 30128181, 2018). "The percentage of high GADD45A expression of breast carcinoma tissues was obviously higher than that of adjacent noncancerous tissues and the difference was statistically significant (P < 0.001)." (PMID 30128181, 2018). "The cytoplasmic staining for GADD45A was identified in the breast carcinoma tissues and adjacent non-neoplastic tissues." (PMID 30128181, 2018). "Studies have shown that GADD45A exhibits context-dependent effects, in that it stimulates proliferation in MYC-driven breast cancers but induces apoptosis and senescence in Ras-driven breast cancers." (PMID 28235006, 2017). "Abnormal methylation of the GADD45A gene promoter region has been found in multiple breast cancer cell lines and breast cancer samples, but not in lymph nodes or normal mammary epithelium." (PMID 26422378, 2015). "Additionally, the correlation of GADD45A expression and clinicopathologic factors is not clear in breast cancer thus far." (PMID 30128181, 2018). "High GADD45A was observed in breast cancer tissues compared with adjacent non-neoplastic tissues." (PMID 30128181, 2018). "However, GADD45A expression was not an independent prognosis factor in TN type breast cancer in multivariate analysis." (PMID 30128181, 2018). "Expression of GADD45A breast carcinoma tissues and adjacent non-neoplastic tissues." (PMID 30128181, 2018). "Although data suggests that Gadd45a may have a function in modulating human breast cancer, thus far there have been no reports on whether the expression of Gadd45a is correlated with any clinicopathological characteristics." (PMID 23706118, 2013). "The expression levels of the GADD45A and ESR1 genes were compared across breast cancer and adjacent non-tumor tissues sourced from patient samples, utilizing curated data from the GEPIA database." (PMID 38732206, 2024).